OR2B2 (olfactory receptor family 2 subfamily B member 2)
Description:
Odorant receptor.
Synonyms: OR6-1; OR2B9; hs6M1-10; OR2B2Q; dJ193B12.4
Tractability: Antibody: UniProt places it where antibodies can reach, with medium confidence; UniProt predicts a signal peptide or a membrane-spanning region; its Gene Ontology location is reachable by antibodies, with medium confidence.
Gene: Protein-coding gene on chromosome 6 (27,911,185 to 27,912,396, reverse strand). Ensembl gene ENSG00000168131.
Subcellular location: Cell membrane
Pathways (Reactome):
Sensory Perception: Expression and translocation of olfactory receptors
Gene Ontology:
Molecular function: olfactory receptor activity; G protein-coupled receptor activity
Biological process: detection of chemical stimulus involved in sensory perception of smell; G protein-coupled receptor signaling pathway
Cellular component: plasma membrane; membrane
Genetic constraint (gnomAD): Loss-of-function variants: 0 observed, 0.2 expected, observed/expected ratio (o/e) 0, 90% interval 0 to 1.88. That is too few expected variants to judge how well the gene tolerates losing a copy. Missense variants: 350 observed, 429.78 expected, observed/expected ratio (o/e) 0.81, 90% interval 0.75 to 0.89. Synonymous variants: 133 observed, 154.02 expected, observed/expected ratio (o/e) 0.86, 90% interval 0.75 to 1.
Homologues: Orthologues: rat Or2b2 (73% identical). Paralogues in human: OR2B6 (70% identical), OR2B3 (63% identical), OR2G3 (52% identical), OR2G6 (50% identical), OR2J3 (50% identical), OR2J2 (50% identical), OR2Y1 (50% identical), OR2B11 (49% identical), OR2G2 (49% identical), OR2J1 (49% identical), OR2H2 (49% identical), OR2W3 (48% identical), and 80 more.
Diseases named in the same sentence as OR2B2 in open-access papers:
OR2B2 is named in the same sentence as 3 diseases in open-access papers, as found by Europe PMC text mining. Sharing a sentence is not in itself a finding about the gene and the disease. The quoted sentences say what the papers report.
Alzheimer disease (1 paper, 2025). A progressive, neurodegenerative disease characterized by loss of function and death of nerve cells in several areas of the brain leading to loss of cognitive function such as memory and language. "In terms of the olfactory receptor gene (OR2B2) this gene has been linked to Alzheimer's disease in a Japanese cohort." (PMID 40364472, 2025).
tumor (1 paper, 2023). "These dose-response results indicate that possibly: (i) the OR2B2 proteins are located in cell membranes and (ii) the presence of odorant molecules may affect the tumor growth in vitro in a dose-response manner." (PMID 37370684, 2023).
OR2B2 also shares sentences with these, for which no sentence is quoted: breast carcinoma (1 paper).